MMP20 (matrix metallopeptidase 20)
Description:
Degrades amelogenin, the major protein component of the enamel matrix and two of the macromolecules characterizing the cartilage extracellular matrix: aggrecan and the cartilage oligomeric matrix protein (COMP). May play a central role in tooth enamel formation. Cleaves aggrecan at the '360-Asn-|-Phe-361' site.
Synonyms: MMP-20; AI2A2
Tractability: Small molecule: a structure with a bound ligand is known; it belongs to a druggable protein family. Antibody: its Gene Ontology location is reachable by antibodies, with high confidence; UniProt places it where antibodies can reach, with medium confidence; UniProt predicts a signal peptide or a membrane-spanning region. PROTAC: ubiquitination databases record sites on it; a small molecule that binds it is known.
Target class: Metallo protease; Metallo protease M10A subfamily; Metallo protease MAM clan; Protease; Enzyme
Gene: Protein-coding gene on chromosome 11 (102,576,832 to 102,625,332, reverse strand). Ensembl gene ENSG00000137674.
Subcellular location: Secreted, extracellular space, extracellular matrix
Pathways (Reactome):
Extracellular matrix organization: Assembly of collagen fibrils and other multimeric structures; Collagen degradation; Degradation of the extracellular matrix
Gene Ontology:
Molecular function: metalloendopeptidase activity; protein binding; zinc ion binding; endopeptidase activity; metallopeptidase activity
Biological process: amelogenesis; collagen catabolic process; extracellular matrix organization; proteolysis; regulation of enamel mineralization
Cellular component: extracellular region; extracellular matrix
Genetic constraint (gnomAD): Loss-of-function variants: 45 observed, 48.19 expected, observed/expected ratio (o/e) 0.93, 90% interval 0.73 to 1.2. The upper end of that interval is the gene's LOEUF score, 1.2, which puts it in group 5 of 6, group 1 being the genes least tolerant of losing a copy. Missense variants: 652 observed, 617.94 expected, observed/expected ratio (o/e) 1.06, 90% interval 0.99 to 1.13. Synonymous variants: 239 observed, 223.82 expected, observed/expected ratio (o/e) 1.07, 90% interval 0.96 to 1.19.
Homologues: Orthologues: chimpanzee MMP20 (99% identical), macaque MMP20 (96% identical), mouse Mmp20 (89% identical), pig MMP20 (89% identical), rabbit MMP20 (89% identical), guinea pig MMP20 (89% identical), rat Mmp20 (88% identical), dog MMP20 (88% identical), tropical clawed frog mmp20 (68% identical), Drosophila melanogaster Mmp1 (33% identical), zebrafish mmp25b (32% identical), zebrafish mmp25a (30% identical), and 8 more. Paralogues in human: MMP3 (45% identical), MMP10 (44% identical), MMP13 (43% identical), MMP8 (43% identical), MMP1 (42% identical), MMP12 (41% identical), MMP27 (40% identical), MMP2 (40% identical), MMP14 (36% identical), MMP24 (35% identical), MMP15 (35% identical), MMP16 (35% identical), and 11 more.
Diseases named in the same sentence as MMP20 in open-access papers:
MMP20 is named in the same sentence as 56 diseases in open-access papers, as found by Europe PMC text mining. Sharing a sentence is not in itself a finding about the gene and the disease. The quoted sentences say what the papers report.
amelogenesis imperfecta (7 papers, 2016 to 2025). Amelogenesis imperfecta (AI) represents a group of developmental conditions affecting the structure and clinical appearance of the enamel of all or nearly all the teeth in a more or less equal manner, and which may be associated with morphologic or biochemical changes elsewhere in the body. "However, mutations inKlk4or Mmp20 or the EMPscannot be interpretedto be responsible for the whole spectrum of enamel phenotypes associated with amelogenesis imperfecta, indicating that the existence of additional enamel-associated proteases." (PMID 28095448, 2017). "Mutations in genes involved in enamel formation, such as enamelin (ENAM), amelogenin (AMELX), matrix metalloproteinase-20 (MMP-20) and kallikrein-related peptidase (KLK4), were associated with amelogenesis imperfecta." (PMID 28697775, 2017). "Failure of the enamel in the Mmp20+/−Klk4+/− molars was unexpected and suggested that digenic effects could contribute to the etiology of amelogenesis imperfecta in humans." (PMID 27066511, 2016).
dental caries (7 papers, 2017 to 2023). The decay of a tooth, in which it becomes softened, discolored, and/or porous. "Yet, the results of other studies of MMP20 SNPs were on the border of significance in 5-year-old Caucasian children with dental caries or have been associated more with poor oral hygiene and dietary habits than the disease itself in 5–14-year-old Caucasians." (PMID 33805090, 2021). "The aim of the study was to analyse Czech children with primary/permanent dentition polymorphisms in those genes encoding MMP2, MMP3, MMP9, MMP13, MMP16, and MMP20, which had been previously associated with dental caries in other populations." (PMID 32398053, 2020). "MMP-1 (collagenase-1), MMP-2 and -9 (gelatinase-A and -B), MMP-3 (stromolysin-1), MMP-8 (collagenase-2) and MMP-20 (collagenase-3) are currently known to participate in dental caries and dental restoration failure." (PMID 36012195, 2022). "During dental caries, MMPs develop proteolytic activity: MMP-20, MMP-2, -3, -9 and -8 are detected in carious dentine in dormant and active forms." (PMID 36012195, 2022). "Additionally, MMP-20 is present in the dentin matrix and is expressed by odontoblasts in mature teeth and activated by dental caries progression." (PMID 30013085, 2018). "Genetic association studies of dental caries have suggested that caries may be influenced by variations in enamel formation genes, such as ameloblastin (AMBN), amelogenin (AMELX), enamelin (ENAM), matrix metalloproteinase 20 (MMP20), tuftelin (TUFT1), and tuftelin-interacting protein 11 (TFIP11)." (PMID 29163197, 2017). "In the context of dental caries progression, both MMPs and cysteine cathepsins are involved, including collagenases (MMP-1, MMP-8), gelatinases (MMP-2, MMP-9), stromelysin (MMP-3), and enamelysin (MMP-20)." (PMID 38001996, 2023).
oral cancer (5 papers, 2018 to 2022). "DSPP gene has been previously linked to oral cancers, but MMP20-DSPP co-localization and interaction has been observed in breast, colorectal and other cancers as well." (PMID 36425062, 2022). "Published reports of the mechanistic network and interplay between these proteins provide a framework for studying their hierarchical interactions with DSPP/MMP20 in oral cancer progression, particularly invasion and metastasis." (PMID 32630820, 2020). "Further studies show that MMP20/DSPP silencing in OSCC cells resulted in the downregulation of oral cancer stem cell markers and increased sensitivity of OSCC cells to cisplatin treatment." (PMID 32630820, 2020). "The present study aimed to investigate the effects of DSPP and MMP20 silencing on specific proteins involved in oral cancer cell adhesion, angiogenesis, metastasis, and epithelial-mesenchymal transition (EMT)." (PMID 32630820, 2020). "The co‐localization and potential MMP20‐DSPP interaction previously reported in oral cancers are present in other cancers." (PMID 30932369, 2019). "The objective of this study was to determine the effects of DSPP/MMP20 gene silencing on oral cancer stem cell (OCSC) markers." (PMID 30002682, 2018). "Although, the mechanisms of DSPP‐MMP20 interactions in cancers have yet to be fully deciphered, our published data showing a ninefold enrichment of DSPP at the MMP20 promoter in oral cancer cell lines suggest a regulatory role for DSPP in the transcription of MMP20." (PMID 30932369, 2019).
ovarian carcinoma (5 papers, 2013 to 2024). A malignant neoplasm originating from the surface ovarian epithelium. "The systematic review on 12 polymorphisms suggested that MMP2 C-735T, MMP7 A-181G, MMP8 rs11225395, MMP9 rs6094237, MMP12 rs2276109, MMP20 rs2292730, MMP20 rs12278250, MMP20 rs9787933 might have a potential effect on ovarian cancer risk." (PMID 28957437, 2017). "Despite initial reports that MMP-20 expression was restricted to enamel, it is expressed in BC cell lines and tissue and promotes invasion in ovarian cancer." (PMID 39127986, 2024). "One study showed that knock-down of MMP20 gene expression in several ovarian cancer cell lines correlated with decreases in cell invasion abilities." (PMID 33914777, 2021). "MMP-19 and MMP-20 protein expression levels from six ovarian carcinoma cell lines (Ovcar5, Ovcar8, Cov362, Ov90, Ho8910 and Skov3) were assayed by western blotting." (PMID 31406154, 2019). "However, it has been reported that KLK4 can be activated by MMP20 during tooth development in the pig suggesting that MMP20 or an MMP with a similar specificity may activate KLK4 in the ovarian cancer microenvironment." (PMID 23451143, 2013). "We found that ovarian cancer cell lines with higher MMP-19 and MMP-20 protein expressing levels were more resistant to anti-cancer drugs, such as A-1210477 and Vincristine." (PMID 31406154, 2019). "Eight polymorphisms (MMP2 C-735T, MMP7 A-181G, MMP8 rs11225395, MMP9 rs6094237, MMP12 rs2276109, MMP20 rs2292730, MMP20 rs12278250, MMP20 rs9787933) were reported associated with ovarian cancer risk, while other polymorphisms could not be associated with ovarian cancer risk." (PMID 28957437, 2017). "Moreover, through experiments using ovarian cancer cell lines, we found cell lines with high MMP-19 or MMP-20 expression levels were more resistant to several anti-cancer drugs." (PMID 31406154, 2019).
dental fluorosis (4 papers, 2020 to 2024). A condition that results from excessive fluoride ingestion during tooth development, resulting in tooth discoloration ranging from white streaks to brown stains and cracks or pits in the tooth enamel. "Matrix metalloproteinase 20 (MMP20) gene variation was present in population with high exposure to fluoride in drinking water and associated with the less sever phenotypes of dental fluorosis." (PMID 33224200, 2020). "The potential role of single nucleotide variants of ODAM, MMP20, and AMELX in the development of dental fluorosis was recently investigated using DNA sequencing." (PMID 36117697, 2022). "Results from this study indicated rs1514392 of ODAM, did not have a significant effect on the severity of dental fluorosis between populations, whilst rs1784418 of MMP20 was significantly associated with susceptibility to dental fluorosis." (PMID 36117697, 2022). "The aim of this study was to investigate the association between dental fluorosis occurrence in children and bone metabolism-related indicators, including bone-specific alkaline phosphatase (BALP), osteocalcin (OC), matrix metalloproteinase (MMP-2, MMP-9, MMP-20), and parathyroid hormone (PTH)." (PMID 39876909, 2024).
lung carcinoma (3 papers, 2016 to 2021). "We have previously used single guide RNA to disrupt the MMP20 gene expression in lung cancer cells, and successfully showed a reduction in cell proliferation and migration, along with significantly reduced activity of PI3-K, and survivin signalling pathways." (PMID 34356991, 2021). "MMP-20, or enamelysin, is a tooth-specific MMP, which under normal conditions is only associated with ameloblasts and odontoblasts but was recently identified in colon, breast, and lung cancers." (PMID 31886121, 2019).
neuroblastoma (2 papers, 2017 to 2024). Neuroblastoma (NB) is the most common solid, extracranial childhood tumor. "We identify a susceptibility locus in MMP20 for 11q-deletion neuroblastoma and subsequently replicate interesting markers in an independent cohort." (PMID 28924153, 2017). "Here we identify common variants at 11q22.2 within MMP20 that associate with neuroblastoma cases harboring 11q deletion (rs10895322), using GWAS in 113 European-American cases and 5109 ancestry-matched controls." (PMID 28924153, 2017). "In summary, here we demonstrate that common variants at the MMP20 locus are exclusively associated with the 11q-deletion subtype of neuroblastoma, indicating that the inherited common variants may contribute to the origin of intra-tumor genetic heterogeneity in neuroblastoma." (PMID 28924153, 2017). "Here, the authors perform a genome-wide association study and identify an association between a variant within a Matrix metalloproteinase (MMP) gene member, MMP20, and 11q-deletion subtype neuroblastoma." (PMID 28924153, 2017). "As the 11q22.2 region harboring MMP20 is commonly deleted in 11q-deletion neuroblastomas, we investigated 11q-deletion cases that are heterozygous (G/A) for rs10895322 and found that the risk allele (G) is preferentially retained in tumors (P = 2.09 × 10−3, binomial test)." (PMID 28924153, 2017). "Future studies addressing the mechanism by which MMP20 impacts tumorigenesis of the 11q-deleted subset of neuroblastoma, which may allow for the development of novel molecular subset-specific therapeutic strategies." (PMID 28924153, 2017).
adenoma (1 paper, 2019). A neoplasm arising from the epithelium. "Although MMP20 levels in inflammatory conditions of the thyroid (subacute thyroiditis, Hashimoto thyroiditis, and Graves disease) and benign thyroid neoplasms (fetal adenoma, adenoma, multinodular goiter) were high, notably higher levels of MMP20 are present in papillary carcinoma." (PMID 30932369, 2019). "Similarly, MMP20 levels in adenocarcinoma grades I, II, III, mucinous adenocarcinoma, and non‐Hodgkin's lymphoma of the colon were very high compared to normal colon, colonic polyps, and adenomas." (PMID 30932369, 2019).
asthma (1 paper, 2023). "We identified two potentially novel (SETDB1 and ZNF8) and five previously reported (DM4C, DOCK8, MMP20, MYL7, and ADCY9) genes associated with increased asthma risk." (PMID 37569643, 2023). "Using follow-up bioinformatics analyses, we also confirmed that two novel genes (SETDB1 and ZNF8) and three previously reported genes (DOCK8, MMP20, and ADCY9) are potential asthma-associated genes." (PMID 37569643, 2023).
benign prostatic hyperplasia (1 paper, 2019). A non-cancerous nodular enlargement of the prostate gland. "MMP20 levels in adenocarcinoma grade II of the prostate were notably higher than in other prostatic neoplasms, including adenocarcinoma grade III, transitional cell carcinoma, leiomyoma, benign prostatic hyperplasia, and chronic prostatitis." (PMID 30932369, 2019).
breast carcinoma (1 paper, 2009). "Except for MMP-20 and -26, the mRNA of all other MMPs was detected in breast cancer tissue as well as in normal breast tissue." (PMID 19531263, 2009).
cervical neoplasms (1 paper, 2019). "Except for SCC of the cervix, which showed high levels of MMP20 (comparable to levels in normal tissue counterpart), other neoplasms of the cervix exhibited relatively low levels of MMP20." (PMID 30932369, 2019). "Accordingly, the potential biologic significance of DSPP and MMP20 levels in the breast, colon, and cervical neoplasms is still unclear." (PMID 30932369, 2019). "Significantly high expression levels of MMP20 and DSPP were observed in the malignant breast, colon, prostate, thyroid, and cervical neoplasms compared with their benign and normal counterparts." (PMID 30932369, 2019). "This study aimed to survey the expression of MMP20 and its cognate DSPP partner in the breast, colon, prostate, thyroid, and cervical neoplasms." (PMID 30932369, 2019).
chronic cervicitis (1 paper, 2019). Chronic inflammation of the cervix. "Intensity of MMP20‐DSPP stain was as high in normal and inflamed cervical (chronic cervicitis) epithelia as in SCC of the cervix." (PMID 30932369, 2019).
chronic prostatitis (1 paper, 2019). An infectious or non-infectious chronic inflammatory process that affects the prostate gland. "Normal prostate tissues showed complete absence of MMP20‐DSPP interaction signals, punctate signals in chronic prostatitis, and distinctly strong interaction signals in hyperplastic and adenocarcinomas of the prostate." (PMID 30932369, 2019).
colon cancer (1 paper, 2025). "A previously performed multi-omics analysis showed the variability of MMP20 gene expression in different databases when colon cancer tissue was compared with normal gut mucosa." (PMID 40724830, 2025). "Based on these results, it could be hypothesized that increased expression of the MMP20 gene, in contrast to other MMP genes, is associated with chemoresistance rather than colon cancer progression." (PMID 40724830, 2025).
colorectal tumors (1 paper, 2022). "MMP20, on the other hand, is a much less investigated member of the MMP family, but was found to be expressed in colorectal tumors in a study with small number of samples." (PMID 35991579, 2022).
cyst (1 paper, 2016). A sac-like closed membranous structure that may be empty or contain fluid or amorphous material. "Surprisingly, the Mmp20+/+Tg maturation stage enamel organ had highly irregular cyst-like rows of ameloblasts that appeared to weave in and out of the section plain (arrowheads), and had a massive cell infiltrate present within what should have been an enamel space." (PMID 27403713, 2016).
diabetes (1 paper, 2022). "The exact effect of diabetes on MMP-20 and KLK4 is still unreported, however, our assumption in this regard is based on the literature published by Bartlett JD." (PMID 35327689, 2022).
Fibroadenoma (1 paper, 2019). A benign tumor of the breast characterized by the presence of stromal and epithelial elements. "Similarly, MMP20‐DSPP staining was of equally high intensity in normal breast ductal epithelial tissue as with fibroadenoma and invasive ductal carcinoma of the breast." (PMID 30932369, 2019).
Hashimoto thyroiditis (1 paper, 2019). An autoimmune disorder caused by the production of autoantibodies against thyroid tissue. "All ranges of cervical epithelia (normal through cancerous) exhibited strong interaction signals for MMP20‐DSPP by iPLA, whereas only Hashimoto thyroiditis and papillary thyroid carcinoma showed strong interaction signals compared to normal thyroid tissue." (PMID 30932369, 2019).
invasive ductal carcinoma of (1 paper, 2019). "With respect to breast tissues, levels of MMP20 in invasive ductal carcinoma of the breast were notably higher than that in hyperplasia, invasive lobular carcinoma, and Paget's disease of the breast." (PMID 30932369, 2019).